TERT (telomerase reverse transcriptase)
Diseases named in the same sentence as TERT in open-access papers (continued):
Sharing a sentence is not in itself a finding about the gene and the disease.
lung carcinoma (144 papers, 2010 to 2025). "Thirty-nine patients were affected with breast, sarcoma, colon, endometrium, and lung cancer cohorts containing TERT mutations at levels comparable to other recurrent mutations in their tumors." (PMID 40578550, 2025). "The 5p15.33 locus near TERT is one of the strongest lung cancer signals and associated with multiple cancers." (PMID 39266564, 2024). "In the context of lung cancer, previous studies have reported associations between genetic variations in TERT and the risk of lung cancer." (PMID 37718447, 2023). "Leave-one-out analyses detected only one outlier, rs7705526 in TERT, resulting in >10% change in MR effect size for associated lung cancer subtypes." (PMID 37079368, 2023). "In the context of lung cancer, genetic variants at several loci have been associated with both LTL and lung cancer risk, including variants near the TERT, TERC, OBFC1, and RTEL1 genes, fundamental to telomere length maintenance." (PMID 37079368, 2023). "TERT rs2736100 C allele has been previously shown to be associated with shorter telomere, lung cancer, and sporadic idiopathic pulmonary fibrosis." (PMID 35159976, 2022). "The eRNA located upstream of telomerase reverse transcriptase (TERT), a well-known predisposition gene for lung cancer, appears to contribute to cancer development by up-regulating TERT expression." (PMID 34073237, 2021). "Inspection at the single SNP level indicated that the lung cancer associations were driven mainly through rs7705526 at the TERT gene locus and rs2293607 at the TERC gene locus." (PMID 33941849, 2021). "Aligned with the TERT promoter mutation frequency that is observed in primary tumors, most lung cancer cell lines were wild-type (WT) while skin cancer lines frequently harbored promoter mutations." (PMID 33924498, 2021). "In lung cancer, a cancer-related SNP, telomerase reverse transcriptase (TERT) rs2736100, was shown to be associated with susceptibility to EGFR mutations in NSCLC." (PMID 33126605, 2020). "This study observed the association between genetic variant rs2853677 of TERT and leukemia and lung cancer in the state of Jammu and Kashmir, India." (PMID 31126249, 2019). "Various genome-wide association studies in different population groups have revealed that polymorphisms in Telomere maintenance gene (TERT) gene located on 5p15.33 is associated with susceptibility to leukemia and lung cancer risk." (PMID 31126249, 2019). "Some genetic variants of TERC (rs10936599) or TERT (rs10069690, rs2242652 or rs2853677) are related with an increased lung cancer risk." (PMID 31052265, 2019). "The results of this meta-analysis suggest that the TERT rs2853669 polymorphism is associated with a significantly increased risk of cancer, particularly lung cancer, in Asian populations." (PMID 29534075, 2018). "In lung cancer, this meta-analysis indicated that the TERT rs2736098 (G > A) polymorphism increased cancer susceptibility in the five genetic models." (PMID 29695979, 2018). "In the case-control study, we investigated the association between SNPs in TERC, TERT genes and the risk of lung cancer in Chinese Han population." (PMID 29299136, 2017). "Between 2015 and 2016, at least 27 studies (6 studies on lung cancer) were published investigating the association between the TERT rs2736100 polymorphism and overall cancer susceptibility." (PMID 28418878, 2017). "In conclusion, our meta-analysis indicated that the TERT rs2736100 polymorphism was associated with increased overall cancer risk, especially lung cancer risk." (PMID 28418878, 2017). "Actually, TERT has been associated with many types of cancer, including lung cancer, urinary bladder, prostate and cervix cancer, and so on." (PMID 28978050, 2017). "We found that the allele “C” of rs10936599 (TERC) and the allele “T” of rs10069690 (TERT) were associated with increased risk of lung cancer (OR = 1.32, 95% CI: 1.12-1.55, P = 0.001; OR = 1.41, 95% CI: 1.14-1.76, P = 0.002, respectively)." (PMID 29299136, 2017).
lung carcinoma (continued). "In conclusion, the study demonstrated that rs10936599 (TERC), rs10069690, rs2242652 and rs2853677 in TERT, and haplotype “TA” of TERT are associated with increased risk of lung cancer in Chinese Han population." (PMID 29299136, 2017). "Five TERC and TERT polymorphisms were genotyped from 554 lung cancer patients and 603 healthy controls." (PMID 29299136, 2017). "The results showed that rs10936599 in TERC and rs10069690, rs2242652 and rs2853677 in TERT were revealed as risk factors of lung cancer." (PMID 29299136, 2017). "Our study indicated that rs10936599 (TERC) and rs10069690, rs2242652 and rs2853677 in TERT and haplotype “TA” of TERT were revealed as risk factors of lung cancer in a Chinese Han population." (PMID 29299136, 2017). "The C allele of rs2853677, however, disrupts the Snail1 binding site and derepresses the expression of TERT by Snail1, blocking the inhibitory effect of Snail1 on tumorigenesis and thus increasing lung cancer susceptibility." (PMID 27191258, 2016). "The rs2736100 C allele has been associated with a higher mRNA expression of TERT when measured in gastric cancer, lung cancer and esophageal squamous cell carcinoma as well as normal tissue adjacent to lung and esophageal squamous cell carcinoma." (PMID 27780202, 2016). "The long TL genetic score was significantly associated with increased risk of lung adenocarcinoma (P = 6.3 × 10−15), even after exclusion of a SNP residing in a known lung cancer susceptibility region (TERT-CLPTM1L) P = 6.6 × 10−6)." (PMID 26138067, 2015). "Many studies have demonstrated the TERT polymorphisms as risk factors for many cancer types, including lung cancer." (PMID 26020272, 2015). "Three genome-wide association study (GWAS) identified susceptibility variants in the telomerase reverse transcriptase (TERT) gene associated with lung cancer risk." (PMID 26020272, 2015). "Two SNPs in TERT (rs2736100 and rs2853676) directly influenced lung cancer risk (OR = 0.76 per T allele, p = 1.2×10−4, FDR q = 2.5×10−4, and OR = 1.17 per A allele, p = 0.031, FDR q = 0.031, respectively)." (PMID 25233467, 2014). "These variants are in linkage disequilibrium (LD) with CLPTM1L and TERT, and both variants are also associated with basal cell carcinoma, lung cancer, glioma and other tumors." (PMID 25007268, 2014). "In a large-scale GWA study, rs2736100 in TERT associated with lung cancer reached GWA significance (p = 4×10−6) and was replicated in an independent set." (PMID 25233467, 2014). "The prevalence of recently uncovered non-coding somatic mutation in promoter region of TERT gene is also to be validated in lung cancer." (PMID 25198510, 2014). "The rs2736098 T allele in TERT gene was associated with a significantly increased risk of lung cancer (P = 0.009 for heterogeneity), with adjusted ORs of 1.27(95%CI = 1.06–1.52)." (PMID 23738012, 2013). "rs401681 is located at 5p15.33, a susceptibility region for lung cancer encompassing two known genes TERT (telomerase reverse transcriptase) and CLPTM1L (cleft lip and palate transmembrane protein 1-like)." (PMID 23653681, 2013). "A common genetic variant, telomerase reverse transcriptase (TERT) rs2736098, was recently reported to be associated with lung cancer risk in Caucasians." (PMID 24260099, 2013). "More recently, a Korean population study of 720 lung cancer patients and 720 healthy controls revealed that the TERT A variant genotype is associated with a significantly increased risk of lung cancer." (PMID 24260099, 2013). "We found that the homozygous variant genetic model of TERT gene was associated with a significantly increased risk of lung cancer with adjusted OR of 1.72(95%CI = 1.19–2.51, P = 0.004 for heterogeneity)." (PMID 23738012, 2013). "The results of our case-control study support 5p15.33 (TERT-CLPTM1L) as a susceptibility region for lung cancer in the Chinese population." (PMID 24260099, 2013).
lung carcinoma (continued). "By contrast, studies in lung cancer showed that risk variants in TERT are associated with longer telomeres, possibly promoting tumorigenesis by increasing the number of cell divisions, leading to acquisition of more somatic changes in DNA." (PMID 23752272, 2013). "A common genetic variant, TERT rs2736098, which is located on chromosome 5p15.33, was recently identified as a susceptibility locus for lung cancer in a combined analysis of Icelandic and European sample sets." (PMID 24260099, 2013). "Many genome-wide association studies(GWAS) of cancer have been reported and provided that the TERT-CLPTM1L genomic region associated the risk of lung cancer." (PMID 23738012, 2013). "The rs2736098 T allele in TERT gene was associated with a significantly increased risk of lung cancer in adenocarcinoma subgroup (P<0.001 for heterogeneity), with adjusted ORs of 1.43(95%CI = 1.17–1.75)." (PMID 23738012, 2013). "TERT is included in the achPathway and its representative SNP rs2736100 has been identified as a lung cancer susceptibility locus in different ethnic populations, especially in Asian populations." (PMID 23469231, 2013). "This same SNP, among others in the region of the CLPTM1L and TERT genes is associated with risk of lung cancer." (PMID 22675468, 2012). "A recent study provides multiple lines of evidence that the lung cancer association of rs31489 in the CLPTM1L gene is an independent observation from the association of rs2376100 in the TERT gene." (PMID 22675468, 2012). "Another study found the allele “C” as a risk allele in lung cancer susceptibility, this agrees with a longer telomere length vulnerability, therefore, our finding suggests that the TERT locus with a shorter TL in the C allele especially in newborns not prone to cancer development." (PMID 38192544, 2024). "We chose the hepatoblastoma cell line Hep-G2 and the lung cancer cell line A-549 for this proof-of-principle study, as they contained two different kinds of variants, namely the activating mutation C228T in the TERT core promoter and the common SNP rs2853669 in the THOR region, respectively." (PMID 37993930, 2023). "TP53BP1 rs560191 may predispose to lung cancer risk depending on the genotypes of either TERT rs2736100 or OBFC1 rs11191865." (PMID 33906323, 2021). "In individuals with the GG genotype of TP53BP1 rs560191, the TT genotype of TERT rs2736100 was significantly associated with an increased risk of lung cancer, compared with the TG and GG genotypes combined after adjustment for potential covariates (OR = 2.58, 95% CI = 1.12–5.94)." (PMID 33906323, 2021). "In addition to its involvement in the development of bladder cancer, mutations in the TERT reporter region have been used in the screening of other cancer types, such as lung cancer." (PMID 31938901, 2020). "Therefore, this study investigated the association between TERT gene polymorphism and lung cancer and leukemia risk in the less explored population of Jammu and Kashmir of North India." (PMID 31126249, 2019). "The haplotype “TA” of TERT was also associated with an increased risk of lung cancer." (PMID 29299136, 2017). "In the allele model, the allele “C” of rs10936599 (TERC) and the allele “T” of rs10069690 (TERT) were found to be associated with increased the risk of lung cancer (OR = 1.32, 95% CI: 1.12-1.55, P = 0.001; OR = 1.41, 95% CI: 1.14-1.76, P = 0.002, respectively)." (PMID 29299136, 2017). "Furthermore, we found that the haplotype “TA” of TERT was associated with a 1.32-fold increased the risk of lung cancer (OR = 1.32, 95% CI: 1.06 - 1.65, P = 0.019)." (PMID 29299136, 2017).
lung carcinoma (continued). "For example, telomerase reverse transcriptase (TERT) promoter mutations are observed in many human epithelial cancers as well as the vast majority of urothelial neuroendocrine carcinomas, however, they are rarely found in NE-prostate or -lung cancers." (PMID 26444865, 2015). "In conclusion, we found that the TERT rs2736098 polymorphism identified in the 5p15.33 region in Caucasians may also predispose to lung cancer, especially adenocarcinomas, in the Chinese population." (PMID 24260099, 2013). "Recently, genome-wide association studies (GWASs) have shown that common TERT-CLPTM1L variants at 5p15.33 may influence the risk of developing lung cancer as well as other types of cancer." (PMID 24386361, 2013). "This SNP is 25 kb upstream from the TERT gene encoding, which encodes the catalytic subunit of telomerase, a reverse transcriptase that affects telomere shortening, which has been implicated in both aging and lung cancer." (PMID 21304900, 2011). "However, association of TERT with leukemia and lung cancer risk in north Indian population groups is still unknown." (PMID 31126249, 2019). "In the subgroup analysis based on cancer type, the TERT rs2736098 with the A allele was 1.299 times more frequent than that with the G allele (OR = 1.299, 95% CI = 1.216–1.386) under the allelic genetic model in lung cancer, and 1.152 times (OR = 1.152, 95% CI = 1.032–1.286) that in bladder cancer." (PMID 29695979, 2018). "Further, ETS2 may reduce TERT promoter activity in lung cancer cells in an allele-specific manner." (PMID 28978027, 2017). "Besides, the haplotype “TA” of TERT gene was also associated with an increased risk of lung cancer." (PMID 29299136, 2017). "Therefore, TERT was considered to be a more plausible candidate at 5p15.33 for lung cancer risk." (PMID 23738012, 2013). "Interestingly, one of the disease-associated variants (rs402710) underlying a GxA cis-eQTL in the cleft lip and palate associated transmembrane protein 1 gene (CLPTM1L) has been previously associated to lung cancer susceptibility and is located in a LD region that includes TERT." (PMID 23889843, 2013). "A comprehensive meta-analysis of publications studying the associations between TERT locus polymorphisms and risk of different cancers in a time span of 2003–2011, has presented a modest risk reduction (per-allele OR = 0.87, 95% CI = 0.84 to 0.89) of rs401681 for lung cancer." (PMID 23653681, 2013). "In contrast, TERT p.C228T mutations and EGFR mutations (p.L858R and E746_A750del) were exclusive to liver and lung cancer, respectively." (PMID 39748775, 2025). "A notable instance is the hypermethylation of the TERT promoter, which has been found to increase TERT expression in most tumor types, including lung cancers." (PMID 39991629, 2025). "TERT is the main component of the telomerase complex, and TERT amplification is often found in early lung cancer." (PMID 39669196, 2024). "In this study, we observed a TERT amplification in 41% of the lung cancer samples, confirming recent studies showing an amplification of TERT in lung cancer cases between 38% and 57%." (PMID 37858127, 2023). "In contrast to TERT the published percentages for amplification of MYC in lung cancer vary more, ranging from 11% to 88%." (PMID 37858127, 2023). "Another study showed that by targeting TERT levels directly with siRNA in A549 lung cancer cells, telomerase activity was reduced." (PMID 36579897, 2023). "Of the nine splicing factors that we screened to be potential TERT regulatory factors, we observed that five splicing factors were related to TERT expression in lung cancer patient samples." (PMID 37531400, 2023). "Telomere shortening has also been linked to lung cancer subtypes and COPD, with the rs2736100 variant of the telomerase reverse transcriptase (TERT) having been shown to be associated with an increased risk of COPD." (PMID 36769181, 2023).
lung carcinoma (continued). "Specifically, we determined that PTBP1 interacts with NOVA1 to promote FL TERT and telomerase activity in lung cancer cells." (PMID 37531400, 2023). "Values per SD of (B) PC2, (C) proliferation score, and (D) telomerase/TERT activity gene expression signatures by lung cancer histological subtypes (TCGA-LUAD and TCGA-LUSC)." (PMID 37079368, 2023). "YAP has been reported to positively regulate TERT expression in the human liver and lung cancer cells." (PMID 36335095, 2022). "BAG6 rs1077393 was the most important predictor among all SNPs in the lung cancer prediction XGBoost model, followed by TERT rs2735845 and CAMKK1 rs7214723." (PMID 35499292, 2022). "TERT promoter hypermethylation was recently shown to upregulate TERT expression in 82% of tumor types, including lung cancers." (PMID 35205708, 2022). "As a result (ORF1F2 = 2.56/2.58*2.92 = 0.34), the multiplicative interaction between TERT rs2736100 and TP53BP1 rs560191 in relation to lung cancer risk was statistically significant (OR for interaction = 0.34, 95% CI = 0.14–0.84)." (PMID 33906323, 2021). "In this study, genotypes of telomere-related polymorphisms (TERT rs2736100, TERC rs1881984 and OBFC1 rs11191865) were determined in 462 lung cancer cases and 379 controls." (PMID 33906323, 2021). "As a classic lung cancer related gene, the expression of two-candidate functional eRNAs in the TERT region were highly correlated with their copy number levels." (PMID 33042282, 2020). "The genetic polymorphisms (rs2853669 in TERT, rs1052133 in OGG1, and rs16969968 in CHRNA5 genes) were shown to be strongly associated with the risk of lung cancer." (PMID 32257438, 2020). "The second is likely to affect the CTCF protein, which regulates the TERT gene and its over-expression is important in lung cancer." (PMID 30458782, 2018). "The 5p15 region containing TERT and CLPM1L genes was thought to be related to lung cancer risk by recent GWA studies in European, East Asian and African – American populations." (PMID 28903315, 2017). "In silico analysis using the cBioPortal for Cancer Genomics showed that the protein KLF4 is deregulated in lung cancer whereas TERT steadily presented amplification." (PMID 27153563, 2016). "TERT (telomerase reverse transcriptase) is another plausible lung-cancer gene candidate which is known for its function in telomere replication and maintenance." (PMID 27323854, 2016). "We performed SNP-SNP interaction testing, WTTc, on lung cancer between rs8034191 and SNPs which are typed and untyped on a 1.8Mb region where both TERT and CLPTM1L are located." (PMID 26187382, 2015). "In several GWA studies, SNPs in TERT and CLPTM1L are associated with overall lung cancer and lung ADC." (PMID 25233467, 2014). "Like the TERT gene, CLPTM1L is also located at 5p15.33, which is a susceptible region for various cancers, including lung cancer." (PMID 25233467, 2014). "The joint effect of TERT and CLPTM1L increased risk for lung cancer with adjusted OR is 1.31(95%CI = 1.00–1.74, P = 0.052 for heterogeneity)." (PMID 23738012, 2013). "Genotype frequencies of the TERT and CLPTM1L polymorphisms among lung cancer cases and controls and their associations with risk of lung cancer." (PMID 23738012, 2013).